TNC (tenascin C)
Diseases named in the same sentence as TNC in open-access papers (continued):
Sharing a sentence is not in itself a finding about the gene and the disease.
tumor (continued). "In our study, tenascin-C and fibronectin expression were significantly increased in the tumor invasive front as compared to the tumor bulk stroma without showing any association with clinicopathological variables." (PMID 28978001, 2017). "TNC, whose expression was shown to be significantly induced after knockdown of ERβ both on the mRNA and protein level, is known to exert important functions in tumor cell invasion." (PMID 28003019, 2016). "We therefore evaluated if the expression of tenascin C in MTC correlates with tumor proliferation." (PMID 27409604, 2016). "Importantly, inflammatory and ECM related proteins characteristic of adipose tissue from obese subjects, such as osteopontin (OPN), chitinase-3 like-1 (YKL-40), tenascin C (TNC) and lipocalin-2 (LCN-2), have also been directly implicated in tumor growth." (PMID 27612200, 2016). "Interestingly, V737N tumours were substantially stiffer than control tumours, suggesting a positive feedback whereby elevated mechanosignalling increases TNC expression to increase ECM stiffness." (PMID 27820599, 2016). "However, the elevated expression of Tenascin C in tumor tissue and corresponding serum levels is in line with the well-established idea of a relationship between inflammation and cancer." (PMID 26967391, 2016). "Moreover, the functional role of Tenascin-C in NSCLC is poorly understood and needs to be investigated in in vitro and in vivo analyses; to increase the knowledge of Tenascin-C associated tumor proliferation and metastatic invasion." (PMID 26967391, 2016). "Tenascin C expression correlates with tumor grade and indicates worse prognosis in several tumors." (PMID 27409604, 2016). "TNC immunoreactivity was extracellular and different expression patterns including predominantly perivascular areas, the central or the border-zone of the tumor tissue, as well as a mixture of these patterns was observed." (PMID 27550150, 2016). "Tumor-specific overexpression of TNC might also be responsible for the highest numbers of peptides targeted by antibody responses among the TAAs analyzed in our study." (PMID 25944688, 2015). "Tenascin C (TNC) establishes interactions between the epithelium and the mesenchyme during embryonic development, tissue differentiation and wound repair but persistent high levels of TNC are present in various tumor tissues, including brain, bone, prostate, intestine, lung, skin, and breast." (PMID 26635612, 2015). "Because elevated tenascin-C expression is often observed in the chronic inflammation of tumor stroma, an analogous mechanism may play an important role in inflammation in the tumor microenvironment." (PMID 25125485, 2014). "It is tempting to speculate that sulfatide might be responsible for the observed improved therapeutic activity of SCN-DOX in tenascin-C expressing tumor model (U-118MG) used here." (PMID 25072631, 2014). "In addition, the library yielded G5, an antibody fragment specific to the alternatively spliced BCD segment of tenascin-C, a marker of angiogenesis and of tumor stroma, which was studied in more detail, because of its possible biomedical applications." (PMID 24950200, 2014). "TNC is highly expressed in tumour stroma and stimulates tumour-cell proliferation." (PMID 23343205, 2013). "However, in our study, the protein expression of TNC was generally limited to the tumor stroma, apart from tumor cell clusters where most of ID3 immunoreactivity was observed." (PMID 23768125, 2013). "The stromal compartment of TNC null mice contained significantly more monocytes/macrophages than the tumor stroma of wild-type mice, suggesting that TNC might promote tumor growth while at the same time blocking the inflammatory infiltrates." (PMID 22481923, 2012). "So far, TNW overexpression has been exclusively described in the context of tumorigenesis and osteogenesis, which suggests that it might be a more specific tumor marker than TNC." (PMID 22947174, 2012).
tumor (continued). "Since elevated tenascin-C expression is often observed in chronic inflammation of tumor stroma, an analogous mechanism may play an important role in inflammation in the tumor microenvironment." (PMID 24212952, 2011). "Moreover, in vitro cell culture models show that, in some cell backgrounds, AD1-containing isoforms promote tumour cell invasion and growth at a higher level than that seen with vector controls and other TNC isoforms." (PMID 20678196, 2010). "Our aim was to study the distribution of these markers in small axillary node-negative breast carcinomas using immunohistochemistry and relate the semiquantitative results to known prognostic factors, the expression of tenascin-C (Tn-C) in invasion border of the tumour and prognosis." (PMID 10389993, 1999). "Similarly, differences in ECM composition, such as laminin, collagen subtypes, and tenascin-C abundance, affect tumor cell adhesion, motility, and migration mode, with murine ECM often exhibiting lower stiffness and distinct integrin-binding profiles than human brain tissue." (PMID 40940872, 2025). "Moreover, phosphorylation state modifications of proteins like TNC, which is involved in metastasis and microenvironment modulation, further indicate post-translational regulation that could influence tumor progression and metastatic potential." (PMID 40861812, 2025). "Therefore, we hypothesized that pGSN may disrupt the oncogenic TNC-integrin feedback loop, thereby eliciting tumor suppressive effects." (PMID 39261905, 2024). "Furthermore, we found TnC is a key component promoting exosome dependent tumor invasion." (PMID 37056561, 2023). "TNC knockdown cells are more sensitive to antiproliferative strategies, which could ultimately lead to novel combinatory antitumor strategies that can target both tumor invasion and proliferation." (PMID 36980765, 2023). "Notably, the expression of TNC at the invasive edge of tumor tissue is higher than its expression in the cancer nest, indicating that there may be a close relationship between the high expression of TNC and tumor migration." (PMID 35444665, 2022). "Tenascin-C can regulate focal adhesion activity, cell migration, extracellular matrix degradation, and epithelial-mesenchymal transition (EMT) processes in a cell-type-specific manner, and this ability to modulate cell behavior is found in various tumor cells and tumor-associated cells." (PMID 35444665, 2022). "We investigated whether TNC influenced expression of the CXCL12 receptors CXCR4 and/or CXCR7 and observed that Cxcr4 levels were higher in TNC‐low (WT/shTNC, KO/shTNC) tumors and in cultured tumor cells upon TNC knockdown, revealing an opposite regulation than Cxcl12 by TNC." (PMID 33988305, 2021). "For example, tenascin C, an ECM protein increased during inflammation, has recently been shown to participate in oral squamous cell carcinoma progression by regulating the migration and the maturation status of tumor-associated myeloid cells and regulatory T lymphocytes through a CCL21/CCR7 axis." (PMID 33936105, 2021). "Indeed, TNC is known to have pleiotropic functions in different cellular contexts, with both autocrine TNC expression in tumor cells and paracrine TNC from stroma in different stages of metastasis; however, the cellular source of TNC in primary PCa was not addressed in our study." (PMID 33334054, 2020). "EDA-containing FN, together with tenascin C, versican and periostin have also been found in other secondary sites prior to tumor cell arrival, and may be important for recruitment of stromal cells as well as for circulating tumor cells to the pre-metastatic niche." (PMID 32426283, 2020). "Several of these stimuli might be relevant for the tumor-specific expression of tenascin-C." (PMID 31032255, 2019).
tumor (continued). "To test whether the S100A9 and TNC serum levels are influenced by other factors, we analyzed correlations between the serum biomarker concentrations and the demographic information, clinical features and tumor characteristics in CRC patients." (PMID 31632476, 2019). "Therefore, we examined whether TNC functions on tumour cell aggression and adhesion ability by activating JNK/Paxillin/FAK signalling." (PMID 29088796, 2017). "Tenascin-C, an adhesion modulatory extracellular matrix molecule, is highly expressed in numerous human malignancies; thus, it may contribute to carcinogenesis and tumor progression." (PMID 26731558, 2016). "The prognostic capability of this antibody response could not only be demonstrated in three different independent study samples in a multicenter setting but was also identified to be independent from known prognostic confounders and the extent of TNC protein expression in the tumor tissue." (PMID 25944688, 2015). "Therefore, isoforms-specific antibodies against TNC can also be used as tumor-specific markers." (PMID 22947174, 2012). "Expression of inflammation-related genes, such as COX2, Stat3, and tenascin C, has been investigated, and the suppression of the resulting inflammatory reactions with non-steroidal anti-inflammatory drugs (NSAIDs) was reported to protect against tumor invasion and metastasis." (PMID 22711317, 2012). "The present study has shown a highly significant association between expression of TNC-AD1 and TNC-AD2 and carcinomas arising in young women (≤40 years), and TNC-AD1 is sometimes incorporated into a novel tumour-associated TNC isoform not detected in normal tissues." (PMID 20678196, 2010). "To generate CARCIK cells with enhanced targeting and penetration of solid tumors, we have designed new CAR molecules against tenascin C (TNC), an extracellular matrix and surface molecule, overexpressed in several tumor types." (PMID 40944718, 2025). "In this context, we detected a significant increase in NGAL, COL1 A1, MMP9, SPP1, TNC and VEGF expression after IL-36 stimulation in HT-29 cells, indicating its potential role in promoting tumour progression through enhanced matrix remodelling." (PMID 40268791, 2025). "We also demonstrated that these cellular features are, at least in part, due to the presence of tumor-supportive molecules such as TNF-α, Tenascin-C, MMP-2, and SDF-1α in the CM secretome of ASCs and OC cells." (PMID 40072102, 2025). "While MMP-9, TNC, and POSTN support tumor progression through ECM remodeling, CD163 is involved in tumoral immune suppression." (PMID 41450913, 2025). "TNC, an important extracellular matrix component, regulates TME through various pathways and plays a vital role in tumor initiation and progression." (PMID 40046232, 2025). "FSP-1+ CAFs have been shown to promote tumor angiogenesis and cell motility and metastasis by producing ECM proteins and secreting cytokines, including tenascin C, matrix metalloproteinases, and vascular endothelial growth factor-A." (PMID 40869109, 2025). "For example, an aptamer targeting an extracellular matrix protein prevalent in gliomas (tenascin-C) was radiolabeled (99mTc) and showed highly specific accumulation in GBM xenografts, with tumor-to-blood signal ratios around 50:1 within hours." (PMID 41245487, 2025). "Particularly, Tenascin-C (TNC) and Tenascin-W (TNW) contribute to tumor progression, metastasis, and resistance to therapy." (PMID 40699660, 2025). "Myofibroblast-like CAFs (myoCAFs) expressing matrix metalloproteinase-11 (MMP11) and tenascin C (TNC) drive matrix sclerosis and tumor dissemination." (PMID 41479912, 2025). "Tenascin-C (TNC) positiveEVs displayed the strongest differences in newly diagnosed and recurrentglioblastoma patients, when compared to non-tumor subjects." (PMID 40056466, 2025).
tumor (continued). "FSP-1+ CAFs promote tumour metastasis by secreting factors such as VEGF-A and Tenascin-C, establishing an angiogenic microenvironment at metastatic sites and providing protection from apoptosis." (PMID 39780187, 2025). "The expression of the epithelial transcript marker EPCAM coincided with the expression of COL18A1, TNC and COL12A1 gene transcripts in the tumor clusters." (PMID 39239354, 2024). "Distinct from numerous oncogenes, TNC is simultaneously involved in tumor angiogenesis, immunomodulation and EMT, which is the reason why TNC has attracted considerable attention in recent years." (PMID 39090080, 2024). "The high level of TNC expression is not limited to the stromal cells; it is also detectable in the sera of NSCLC patients and shows a correlation with tumor size, the spread of cancer to lymph nodes, and the overall survival of patients." (PMID 39403603, 2024). "The results revealed significant differences between the tumor and paratumor tissues regarding the expression of FAP, secreted protein acidic and cysteine rich (SPARC), and tenascin C (TNC), which are closely related to HSCs’ function." (PMID 38740736, 2024). "To test its expression in metastases from different primary tumor types and at different metastatic sites, we stained a tissue microarray (TMA) of multiple human metastases for the expression of TNC protein." (PMID 37098922, 2023). "As proof of concept, selective and high-affinity nanobodies were isolated against an example protein from this signature, tenascin-C (TNC), known to be abundant in many tumor types and to play a role in metastasis." (PMID 37098922, 2023). "Estrogen activity can modulate components of the ECM in the tumor microenvironment, upregulating transcripts of COL1A1, and several matricellular proteins such as TNC, FN1, and POSTN." (PMID 37056757, 2023). "Higher expressions of the genes involved in the Tumor Microenvironment Pathway, including ICAM1, SLC2A1, and TNC were found in the PMCs of the LCP group." (PMID 37649596, 2023). "TNC has been identified to regulate tumor angiogenesis and tumor immunity, especially the function of CTL, plasticity, and tumor metastasis in multiple cancers." (PMID 37784082, 2023). "The FAP mRNA levels showed a significant positive correlation with the ACTA2, COL11A1, TNC, and PDPN genes in PanCK(-) AOIs at EOCC tumor invasive margin." (PMID 37964075, 2023). "Researches have showed that secreted factors released from the primary tumor can change the expression of ECM proteins such as FN and TnC, which enhances the ability of BC cells to colonize the lung and form overt lung metastases 33-35." (PMID 37056561, 2023). "The overexpression of a large glycoprotein, tenascin-C, in the tumour ECM is corelated with tumour metastasis." (PMID 37686652, 2023). "We first confirmed downregulation of the most significantly depleted gene of the EMT gene set, the glycoprotein Tenascin-C (Tnc), by qPCR on additional KPC-Sf3b1K700E/+ tumor samples and by histology in KPC-Sf3b1K700E/+ PDAC sections." (PMID 37823551, 2023). "By focusing on three matrix components typically up-regulated in the tumor microenvironment (TME) of iCCA (POSTN, TnC, and OPN), we also evaluated their effects on the biology of iCCA cells." (PMID 36902188, 2023). "As an example, VHH targeting Tenascin-C, a component of the ECM involved in tumor progression and the immune-suppressive tumor microenvironment, allows tumor visualization." (PMID 37686035, 2023). "On the other hand, the results showed that, for LUSC tumor samples, CDH2, SPP1, and TNC were significantly upregulated and FN1, CYR61, SERPINA1, and IL6 were significantly downregulated compared to their respective controls." (PMID 37887075, 2023). "Several soluble mediators produced by ascites-derived TAMs, e.g., TGFß1 protein, tenascin C (TNC) and fibronectin (FN1), activated tumor cell migration." (PMID 35682890, 2022).
tumor (continued). "Macrophages are known to promote tumor cell migration through the secretion of proteins, such as EGF, CHI3L1, IGF1, FN1, TNC and TGFBI." (PMID 36551640, 2022). "The role of five of them (LAMB2, SERPINEE1, ITGB1, TNC, and LAMA5) in tumor growth has been well established." (PMID 35642785, 2022). "TNC and CD209 genes play an important role in the progression of GBM by regulating the migration, adhesion, and invasion of tumor cells into adjacent tissues." (PMID 35992881, 2022). "In support, TNC-KD reduced stiffness in a GBM xenograft model and prolonged survival of the tumor mice." (PMID 36102918, 2022). "PDGFRβ activation then leads to ECM remodeling, including TNC upregulation, and promotes CAF migration and CAF-induced tumor cell invasion." (PMID 36003785, 2022). "Tenascin-C is expressed in response to strain in fibroblast cell lines, organizes and bundles other ECM proteins in the tumor microenvironment, and portends poor LUAD prognosis." (PMID 36279309, 2022). "CAFs can also influence tumor invasion trough indirect actions such as the overproduction of ECM components (collagen, tenascin-C, fibronectin or hyaluronate) that favor tumor cell proliferation and invasion, leading to metastasis." (PMID 36139572, 2022). "Within tumor regions, we used markers informed by scRNA-seq analysis to identify CAF1 (SMA and VIM) or CAF2 (TNC and PDGFRα) populations." (PMID 35600339, 2022). "TNC is an important component of the ECM and is mainly expressed during tissue repair and tumor growth." (PMID 36421704, 2022). "ITGB1 and ITGA1 were found among the key CAF receptors that mediate crosstalk between tumor cells and CAFs by interacting with COL1A1 and TNC and, thereby, modulating the TME." (PMID 36003785, 2022). "Combinational therapy with monoclonal antibodies that inhibited TnC-mediated TLR4 activation and anti-PD-L1 treatment significantly reduced tumor growth and lung metastasis in vivo." (PMID 33981316, 2021). "The expression of some proteins, including COX-2, TNC, and others, are related to LVSI, tumor microenvironment, and inflammation." (PMID 34320931, 2021). "Both TNC and POSTN are members of the core matrisome, which is involved in the creation of the so-called metastatic niche of human neoplasms such as colorectal cancers, brain, and breast tumors." (PMID 34944807, 2021). "In our study, the expression of POSTN, TNC, CAV1 and FSCN1 found to be localized predominantly in the cytoplasm of the tumour cells." (PMID 33739025, 2021). "The extracellular matrix (ECM) molecule tenascin-C (TNC) is highly expressed in malignant tumors including HNSCC and plays multiple roles in the tumor microenvironment (TME) promoting cancer progression and metastasis." (PMID 34290694, 2021). "The rodent involuting liver is enriched for collagen I, fibronectin, and tenascin-C, ECM proteins demonstrated to promote establishment of tumor cells in the niche." (PMID 33916683, 2021). "The expression of POSTN, TNC, CAV1 and FSCN1 was localized predominantly in the cytoplasm of the tumour cells." (PMID 33739025, 2021). "Recently, anti-tenascin-C single domain nanobodies have been developed that may also prove useful in a variety of imaging or compound-delivery applications, and other emerging techniques use radiolabeled or fluorescence-labelled tenascin-C aptamers for tumour detection." (PMID 34564696, 2021). "Here, we stained for TNC and saw a similar staining pattern as for ERTR7, separating tumor cells (p63+), supportive of FRC also expressing TNC in this model." (PMID 34290694, 2021). "By examining these genes via ingenuity pathway analysis, tenascin C emerged as a promising candidate linking MET signaling and tumor microenvironment." (PMID 34298732, 2021). "Tenascin-C (TNC), a major component of the ECM, activates the JNK pathway to promote tumor invasion in GBM." (PMID 33096780, 2020). "Tenascin-C (TNC) has been demonstrated to have an angiogenic role in GBM; ezrin to inhibit NF2 tumor-suppressor in GBM." (PMID 33374813, 2020).